SOX2 (SRY-box transcription factor 2)
Diseases named in the same sentence as SOX2 in open-access papers (continued):
Sharing a sentence is not in itself a finding about the gene and the disease.
small cell lung carcinoma (39 papers, 2007 to 2026). Small cell lung cancer (SCLC) is a highly aggressive malignant neoplasm, accounting for 10-15% of lung cancer cases, characterized byrapid growth, and early metastasis. "Antibodies against SOX2 have been detected in some small cell lung cancer patients, which may be associated with better prognosis." (PMID 39286028, 2024). "Neuronal subtypes express neuroendocrine markers such as SOX2 and synaptophysin and require small-cell lung cancer–like chemotherapy regimens." (PMID 40735045, 2025). "Validation through qRT-PCR in 30 MTCs demonstrated upregulation of ASCL1, DLL3, and SOX2 in high-grade MTCs, a gene signature akin to small-cell lung carcinoma, molecular subgroup A. Subsequently, DLL3 expression was validated by immunohistochemistry." (PMID 38958823, 2024). "The decrease of YAP/TAZ level can down-regulate the expression of SOX2 and other stem genes in small cell lung cancer (SCLC) CSCs, thereby enhancing chemosensitivity and cell death." (PMID 38561775, 2024). "A recent report found that SOX2 mediates cisplatin resistance in small cell lung cancer with downregulated expression of hsa-miR-340-5p." (PMID 35059870, 2022). "The Sox2 gene is frequently amplified in small-cell lung cancer cells obtained from primary cells and cell lines." (PMID 26880969, 2016). "SOX2 is frequently amplified at a percentage of around 20% in small cell lung cancer (SCLC) and NSCLC." (PMID 27528220, 2016). "Overexpression of SOX2 is found in adenocarcinoma, squamous cell, large-cell, and small-cell lung carcinomas, where it promotes tumorigenesis and maintenance of cancer stem cell characteristics." (PMID 24889513, 2014). "SOX2 amplification has previously been found in several cancer types including glioblastoma, small-cell lung cancer (SCLC) and many forms of squamous cell carcinoma (SCC)." (PMID 25114775, 2014). "Sox2 was found to be frequently downregulated in gastric cancers and overexpressed in small-cell lung cancers, esophageal squamous carcinomas, and basal cell-like breast carcinomas." (PMID 22069467, 2011). "A reduction in hsa-miR-340-5p expression might influence cisplatin resistance by mediating SOX2 expression in small-cell lung cancer cells." (PMID 40561678, 2025). "Besides small-cell/neuroendocrine PC, other neuroendocrine tumors have been described to express SOX2, such as small-cell lung cancer and Merkel cell carcinoma of the skin." (PMID 26540632, 2016). "However, a study reported that downregulation of Sox2 inhibits cell proliferation in small cell lung cancer." (PMID 26871472, 2016). "In addition, the Sox2 locus was shown to be amplified in small-cell lung cancer, esophageal squamous carcinomas, and, to a lesser extent, in GBM." (PMID 22069467, 2011). "Small-Cell Lung Cancer (SCLC) develops in 50% of people with Lambert-Eaton Myasthenic Syndrome (LEMS), and SOX2 has been demonstrated to be an effective method for predicting SCLC in LEMS patients." (PMID 39192657, 2025). "A recent study has also suggested that elevated expression of both SOX2 and FGFR1 is correlated to poor prognosis in small cell lung cancer." (PMID 25010701, 2014). "Moreover, upregulated SOX2 contributed to the stemness and metastasis of small cell lung cancer (SCLC) cells, while inhibition of the AhR signaling pathway blocked benzo(a)pyrene-induced protein kinase A (PKA) expression and downstream PKA/SOX2 axis." (PMID 38791215, 2024). "In small cell lung cancer (SCLC), ASCL1 and NEUROD1 could regulate various genes such as SOX2, MYCL1, that contribute to neuronal function and promote perineural invasion." (PMID 36376881, 2022).
small cell lung carcinoma (continued). "Thus, SOX1, SOX2, SOX3 and SOX21 as well as SOX4 were demonstrated to elicit humoral immune responses in small cell lung cancer patients." (PMID 17375044, 2007). "Inhibition of PFKFB3 by the glycolytic inhibitor PFK158 and by shRNA stable knockdown in small cell lung carcinoma (SCLC) cell lines inhibited glycolysis, proliferation, spheroid formation, and the expression of cancer stem cell markers CD133, Aldh1, CD44, Sox2, and ABCG2." (PMID 35804016, 2022).
teratoma (37 papers, 2008 to 2026). A non-seminomatous germ cell tumor characterized by the presence of various tissues which correspond to the different germinal layers (endoderm, mesoderm, and ectoderm). "SOX2, a marker protein for cell pluripotency, suggests the possibility of further differentiation and therefore indicates the likelihood of teratoma formation." (PMID 41362729, 2026). "In a case of a coccygeal teratoma in a cat, Sox2 was expressed in a transition stage from immature to mature non-myelinating Schwann cells, in immature, odontogenic epithelial cells and in immature, endodermal cells." (PMID 40217475, 2025). "Atoh8 KD established iPS lines expressed similar Oct4, Sox2 and Nanog levels to controls and differentiated into three germ layers in teratoma." (PMID 36075976, 2022). "In the present study, our finding indicated that, transfection with Oct4/Sox2/Klf4/Parp1(OSKP) were capable of the generation of OSKP-iPSCs that formed smaller teratoma than iPSCs reprogrammed with the conventional reprogramming factors Oct4/Sox2/Klf4/c-Myc." (PMID 29719629, 2018). "We were able to evaluate SOX2 by quantitative RT-PCR in 34 of the samples included in our analysis (N = 17 teratomas)." (PMID 23806198, 2013). "It has also been shown to directly repress Sox2 expression in mice and when down regulated increase teratoma formation." (PMID 22737227, 2012). "RTT iPSCs expressed pluripotency markers Sox2, Oct4, Tra1-60, and Tra1-81 and maintained hESC-like morphology upon passaging for at least 42 passages with normal karyotype (46, XX), and were pluripotent as indicated by teratoma formation." (PMID 32851591, 2021). "In addition, these models utilize transduction of fibroblast with retroviruses encoding OCT4, SOX2, KLF4 and c-MYC, which are by and large cancerous and form teratomas." (PMID 25140287, 2014). "Notably, SOX2 was included in four of the pathways that differed between mature and immature teratomas." (PMID 23806198, 2013). "Further, hAEC transplantation appears to be safe and tumour or teratoma formation has not been demonstrated in spite of Oct-4, Sox-2 and Nanog expression that are linked to teratoma formation by embryonic and induced pluripotent stem cells." (PMID 22073147, 2011). "We characterized iPSCs by demonstrating the gene expression of the PSC markers OCT4, SOX2, TRA-1-60, and NANOG, teratoma formation, and differentiation into three germ layers." (PMID 36614165, 2022). "The isolated hiPSC colonies were cultured in E8 culture medium, and further verified by expression of pluripotency markers NANOG, SOX2, OCT4 and TRA-1-60, and formation of embryoid bodies (EBs) and teratoma with three germ layers." (PMID 29523209, 2018). "We also confirmed that all the patient-derived iPSC lines expressed the embryonic stem cell markers OCT3/4, SOX2, NANOG, REX1, MYC, and KLF4 and were capable of forming teratomas." (PMID 29088246, 2017). "It expressed genes involved in stemness (OCT3/4, SOX2 and NANOG), was able to generate teratoma in immunodeficient SCID mice and to differentiate into early mesodermal, endodermal and ectodermal cells as shown by the expression of specific markers." (PMID 27043207, 2016). "Most importantly, NP cultures from all three lines demonstrated significantly low or undetectable levels of NANOG, SOX2 and OCT4 mRNA transcripts, which is essential in preventing teratoma formation in vivo." (PMID 25635918, 2015). "Furthermore, the mRNA expression of canine endogenous OCT4, SOX2, and NANOG significantly increased, confirming the multi-differentiation potential of cells after embryoid and teratoma formation." (PMID 40531862, 2025). "Previous studies have shown that AFMSCs obtained from early and second-trimester AF can express various ESCs markers such as OCT-4, SOX2, NANOG, SSEA4, and TRA1-81, which may raise the concern of teratoma formation post-transplantation." (PMID 38085460, 2024).
teratoma (continued). "Pluripotency of stem cells can be identified by RT-PCR of ESC markers (i.e. Oct4, Sox2 and Nanog, immunofluorescence staining with stage-specific embryonic antigens (Oct4, Sox2, Nanog, SSEA-3, SSEA-4, TRA-l-60 and TRA-1-81), alkaline phosphatase activity and teratoma assay." (PMID 35575836, 2022). "In this study, we revealed that Sox2 T258 O-GlcNAcylation positively affects ESC self-renewal and is important for the repression of mesendodermal genes during the early differentiation stage of teratoma formation." (PMID 34819616, 2021). "The results showed iPSC could express pluripotency markers such as OCT4, SOX2, and NANOG and form an embryoid body and a teratoma." (PMID 33224204, 2020). "SOX2 is found to be an absolute marker for EC in combination with OCT3/4, although it can also be found more heterogeneously in differentiated components, especially teratoma." (PMID 24404135, 2014). "Although a combination of qRT-PCR, immunocytochemistry, and flow cytometer analysis did not detect the expression of Oct4, Sox2, Nanog, or Ssea1, it is still feasible that these cell masses could be teratomas originating from rare GFP-negative partially pluripotent cells contaminating iHepL cells." (PMID 27460218, 2016). "However, the decreased levels of NANOG and SOX2 observed upon HMGB1 or HMGB1/2 double KD had no impact on the pluripotency of hESCs, as revealed using a teratoma formation assay, in which no tangible deviation from the normally differentiated teratoma morphology was demonstrated." (PMID 33076532, 2020).
seminoma (36 papers, 2012 to 2026). A radiosensitive malignant germ cell tumor found in the testis (especially undescended), and extragonadal sites (anterior mediastinum and pineal gland). "We analyzed microarray expression data of TCam‐2 cells grown over six weeks (w) in vivo and reprogrammed into an EC‐like cell fate (T 1w‐6w, in duplicates) and in vivo‐grown SOX2‐deficient TCam‐2 cells (maintain a seminoma cell fate)." (PMID 34293822, 2022). "Under in vitro differentiating conditons both, the parental and SOX2-deficient TCam-2 cells downregulated pluripotency/seminoma markers OCT3/4, TFAP2C, PRDM14 and PRAME, while SOX2 and DNMT3B expression remained low." (PMID 27283990, 2016). "Subsequently, a gene expression analysis via RT-qPCR was performed for the non-seminoma marker SOX2; the cytokine IL6, which is moderately produced also through tumor cells; and the proliferation and cell cycle genes KI67 and CDK4." (PMID 37174085, 2023). "Previously published work identified SOX2 as a key player for reprogramming Tcam-2 cells from a seminoma phenotype to a more EC-like fate." (PMID 35269507, 2022). "We stratified the TCGA testicular cancer cohort into seminomas (SOX17+) and non-seminomas (SOX2+ (EC), AFP+ (yolk-sac tumor), beta-hCG+ (choriocarcinomas)." (PMID 32272809, 2020). "Deletion of SOX2 interferes with this reprogramming, prolonging the seminoma fate of TCam-2 to six weeks." (PMID 31130628, 2019). "Our results establish FOXA2 (in addition to SOX2) as an essential factor driving reprogramming and differentiation of seminoma-like TCam-2." (PMID 31130628, 2019). "Upon loss of SOX2 and FOXA2, TCam-2 maintained a seminoma cell fate for at least twelve weeks, demonstrating that both factors are key players in the reprogramming to an EC-like cell fate." (PMID 31130628, 2019). "Our results further strengthen the idea that seminomas show a plasticity, which is influenced by the microenvironment and regulated by SOX2 and FOXA2." (PMID 31130628, 2019). "So, it seems that SOX2 is required for reprogramming of seminomas into an EC, but dispensable for a direct differentiation into a mixed non‐seminoma." (PMID 28244655, 2017). "Molecular analyses of the tumors demonstrated a seminoma-like morphology and gene expression profile, suggesting that SOX2 is essential for induction of an EC-like cell fate." (PMID 27283990, 2016). "The fact that these factors are strongly upregulated during the seminoma to EC transition of TCam-2, suggests that SOX2 induces expression of these genes." (PMID 27283990, 2016). "In summary, in SOX2 depleted clones expression of seminoma markers is maintained and the initial reprogramming markers, pluripotency genes and epigenetic factors are not induced." (PMID 27283990, 2016). "In conclusion, SOX2 is an essential factor in acquiring the EC-like cell fate from GCNIS or seminoma." (PMID 27283990, 2016). "Both, seminomas and EC express the pluripotency markers OCT3/4 and NANOG, but expression of the pluripotency factor SOX2 is restricted to ECs, while seminomas express SOX17 instead." (PMID 26226633, 2015). "Apart from these common markers, SOX2 has been suggested to distinguish between the two histological subtypes, expressed only in non-seminomas." (PMID 23969837, 2013). "The detection of SOX2 in seminoma cells TCam-2 is inconsistent with other authors, though it was described later that this cell line also features non-seminomatous characteristics." (PMID 23969837, 2013). "The marker genes SOX17 and SOX2 are differentially expressed between seminoma and ECs and serve as marker for transition." (PMID 24386123, 2013). "In contrast, non-seminomas are transformed germ cells that have reactivated pluripotency, as evidenced by the expression of SOX2, OCT3/4 and NANOG, three main regulators of pluripotency." (PMID 23068969, 2012).
seminoma (continued). "According to earlier publications, each histologic subtype has different gene signatures identified by transcriptional profiling: seminomas have overexpressed spermatogenesis-associated genes like PRAME, MAGEA4 and SPAG1 while NSGCTs have overexpressed regulatory genes such as DNMT3B and SOX2." (PMID 40011822, 2025). "We also checked whether SOX17, which in part shows redundancy to SOX2 in regulating pluripotency in seminomas, binds to CD24 as well." (PMID 34293822, 2022). "In the SOX17+/SOX2‐/CD24‐ seminoma cell line TCam‐2, only negligible binding intensities of SOX17 to CD24 could be detected (peak intensities < 15)." (PMID 34293822, 2022). "Furthermore, SOX17 is highly expressed in seminomas, where it is thought to support pluripotency by functionally replacing SOX2." (PMID 31130628, 2019). "Indeed, CRISPR/Cas9 SOX2-deleted TCam-2 cells were able to maintain a seminoma-cell fate in vivo for about six weeks, but after six weeks in vivo still small sub-populations initiated differentiation." (PMID 31130628, 2019). "So, SOX2 is an essential factor in acquiring an EC-like cell fate from seminomas." (PMID 27283990, 2016). "Additionally, many pluripotency and EC associated genes, like SOX2, ZIC3, ZFP42, LIN28, SALL4 and PRDM14 were upregulated without correlating to changes in their 5mC status, while seminoma markers SOX17, cKIT, PRDM1 and PRAME were downregulated." (PMID 27283990, 2016). "In summary, the deficiency of SOX2 does not impair the in vitro differentiation process of TCam-2 cells into a cell type resembling a mixed non-seminoma, further demonstrating that no EC intermediate state is necessary." (PMID 27283990, 2016). "In fact, SOX2 and SOX17 serve as markers for diagnostic discrimination between seminomas and ECs." (PMID 27283990, 2016). "Furthermore, additional EC and pluripotency genes were upregulated (SOX2, LEFTY1 /2, DNMT3L, SALL4, DPPA5, BCAT1, FZD7, LIN28, ZIC3), while seminoma-associated genes where downregulated (SOX17, TFAP2C, cKIT, PRAME), without changing 5mC-levels." (PMID 26226633, 2015). "Thus, SOX2 is the driving force behind the reprogramming of seminomas to an EC‐like state." (PMID 28244655, 2017). "Overall, seminomas more strongly resemble PGCs and express pluripotency genes, particularly OCT3/4, SOX2, and NANOG." (PMID 38791003, 2024). "Two precursor lesions for testicular germ cell tumors type II, germ cell neoplasia in situ (GCNIS) and microinvasive germ cell tumor (MGCT), and seminoma (SE) also express an OSKM panel, with SOX17 as substitute for SOX2." (PMID 36835562, 2023). "ECs and seminomas express the pluripotency markers NANOG and OCT3/4, but SOX2 is detected in ECs only and is thought to be compensated by SOX17 in seminomas." (PMID 27283990, 2016). "In these somatic microenvironments, TCam-2 cells upregulate EC-markers SOX2, CD30, DNMT3B/L and downregulate seminoma markers SOX17, cKIT and PRDM1." (PMID 26226633, 2015). "Among them, GDF3, NODAL, LEFTY1 /2, GAL, DPPA3, SOX2, DNMT3B /L, DPPA5, BCAT1, FGF2, PRDM14, ZIC3 and FZD7, while seminoma markers SOX17, cKIT and PRAME were downregulated." (PMID 26226633, 2015). "Given the high similarity between SOX factors and that SOX2 and SOX17 share similar functions in regulating pluripotency in ECs and seminomas, respectively, it seems reasonable that both factors are able to switch their functions in dependency of the interacting partner." (PMID 33448076, 2021). "LHR029 also detected LHCGR in the cytoplasm of a subset of SOX2 positive EC cells while LHRsc showed no expression in non-seminoma components." (PMID 32466562, 2020). "Most TCam-2 cells lacking SOX2 maintain a seminoma-like morphology, gene expression and DNA methylation profile for at least six weeks." (PMID 31130628, 2019). "Next, we confirmed that SOX2- and FOXA2-deficient TCam-2 cells do not differ from the parental TCam-2 cells with regard to proliferation and gene expression of typical GCNIS/seminoma and differentiation markers." (PMID 31130628, 2019).
seminoma (continued). "Positive staining was demonstrated in seminoma for Nanog (red), OCT4 (brown), and SALL4 (brown); skin for SOX2 (brown); and tonsil for pSTAT3 (brown) and CD44 (brown)." (PMID 29046873, 2017). "Thus, in undifferentiated seminomas it is highly likely that SOX17 is redundant to SOX2 and promotes expression of pluripotency factors in combinaton with OCT3/4, thereby maintaining a GCNIS/seminoma-like cell fate." (PMID 27283990, 2016). "Consequently, TCam‐2 cells deficient for SOX2 and FOXA2 were not able to differentiate into non‐seminoma‐like cells at all." (PMID 33448076, 2021). "Furthermore, we postulated that during the seminoma to EC transition, inhibition of BMP signaling leads to derepression of SOX2, restoring the classical pluripotency circuitry found in ECs and ESCs, subsequently leading to upregulation of ZIC3, which in turn helps to maintain NODAL signaling." (PMID 27283990, 2016). "Indeed, as expected no SOX2 is expressed, in line with the seminoma type of cells, linked to expression of SOX17 instead of SOX2." (PMID 24404135, 2014). "Seminomas typically express SOX17 in their nuclei and are negative for SOX2, known to be not expressed in human PGCs, while EC cells express SOX2 and are negative for SOX17." (PMID 34205983, 2021). "We stratified the TCGA dataset of 156 samples into a seminoma expression signature (SOX17, PRAME, PRDM1 positive; SOX2, DNMT3B, GAL negative) and an EC expression signature (SOX2, DNMT3B, GAL positive; SOX17, PRAME, PRDM1 negative)." (PMID 32418994, 2020). "In TCam-2-ΔSOX2 cells, the switch from SOX17 to SOX2 is not possible and prolonged expression of SOX17/OCT3/4 contributes to maintenance of a seminoma fate." (PMID 27283990, 2016).